COL6A2 (collagen type VI alpha 2 chain)
Description:
Collagen VI acts as a cell-binding protein.
Synonyms: BTHLM1; BTHLM1B; PP3610; UCMD1; UCMD1B
Tractability: Antibody: UniProt places it where antibodies can reach, with high confidence; its Gene Ontology location is reachable by antibodies, with high confidence; UniProt predicts a signal peptide or a membrane-spanning region. PROTAC: ubiquitination databases record sites on it. Other modalities: an approved drug acts on it.
Gene: Protein-coding gene on chromosome 21 (46,096,722 to 46,132,851, forward strand). Ensembl gene ENSG00000142173.
Subcellular location: Secreted, extracellular space, extracellular matrix; Membrane
Subcellular location (Human Protein Atlas): Cytosol; Plasma membrane; Predicted to be secreted
Pathways (Reactome):
Extracellular matrix organization: Assembly of collagen fibrils and other multimeric structures; Collagen biosynthesis and modifying enzymes; Collagen chain trimerization; Collagen degradation; ECM proteoglycans; Integrin cell surface interactions
Developmental Biology: NCAM1 interactions
Signal Transduction: Signaling by PDGF
Gene Ontology:
Molecular function: collagen binding; extracellular matrix structural constituent conferring tensile strength; protein binding
Biological process: response to glucose
Cellular component: extracellular exosome; extracellular matrix; extracellular region; extracellular vesicle; plasma membrane; protein-containing complex; collagen type VI trimer; endoplasmic reticulum lumen; microfibril; membrane; sarcolemma
Genetic constraint (gnomAD): Loss-of-function variants: 90 observed, 119.79 expected, observed/expected ratio (o/e) 0.75, 90% interval 0.63 to 0.89. The synonymous counts are far from expectation, so gnomAD's model fits this gene poorly and the ratio says little. Missense variants: 1,607 observed, 1,509.9 expected, observed/expected ratio (o/e) 1.06, 90% interval 1.02 to 1.11. Synonymous variants: 793 observed, 615.89 expected, observed/expected ratio (o/e) 1.29, 90% interval 1.21 to 1.37.
Gene-disease validity (ClinGen):
ClinGen rates the evidence that COL6A2 causes each of these diseases.
collagen 6-related myopathy (autosomal dominant; autosomal recessive): Definitive. A qualitative or quantitative defect of collagen 6 disorder that covers a wide spectrum of musculoskeletal phenotypes caused by dominant and recessive mutations in the three major collagen VI genes: COL6A1, COL6A2, and COL6A3.
Homologues: Orthologues: macaque COL6A2 (98% identical), mouse Col6a2 (91% identical), guinea pig COL6A2 (90% identical), dog COL6A2 (89% identical), rat Col6a2 (83% identical), pig COL6A2 (73% identical), tropical clawed frog col6a2 (65% identical), zebrafish col6a2 (61% identical). Paralogues in human: COL6A1 (35% identical), COL2A1 (25% identical), COL5A1 (24% identical), COL5A2 (24% identical), COL1A1 (23% identical), COL11A1 (23% identical), COL11A2 (23% identical), COL3A1 (22% identical), COL4A5 (22% identical), COL4A2 (22% identical), COL1A2 (22% identical), COL5A3 (22% identical), and 25 more.
Diseases named in the same sentence as COL6A2 in open-access papers:
COL6A2 is named in the same sentence as 136 diseases in open-access papers, as found by Europe PMC text mining. Sharing a sentence is not in itself a finding about the gene and the disease. The quoted sentences say what the papers report.
Ullrich congenital muscular dystrophy (36 papers, 2010 to 2025). Ullrich congenital muscular dystrophy (UCMD) is characterized by early-onset, generalized and slowly progressive muscle weakness, multiple proximal joint contractures, marked hypermobility of the distal joints and normal intelligence. "Mutations in the genes encoding COL6A1 and COL6A2 have been associated with certain diseases, including Bethlem Myopathy and Ullrich Congenital Muscular Dystrophy." (PMID 37842511, 2023). "It has been suggested that at least some cases of Ullrich’s disease are caused by recessive mutations in COL6A2." (PMID 38065855, 2023). "COL6A1/COL6A2/COL6A3 mutations cause severe Ullrich congenital muscular dystrophy (UCMD) and milder Bethlem myopathy, which can be inherited as autosomal dominant or recessive disorders, but collagen VI mutations can also affect the skin and tendon." (PMID 31387942, 2019). "Interestingly, a number of mutations in COL6A2 have been observed in muscular disorders, including Bethlem myopathy and Ullrich congenital muscular dystrophy." (PMID 20374639, 2010). "This group includes collagen VI‐related dystrophies such as Ullrich congenital muscular dystrophy (UCMD) and Bethlem myopathy (BM), caused by mutations in the COL6A1, COL6A2 and COL6A3 genes." (PMID 39523858, 2024). "By contrast, Stickler syndrome has the most collagens (six) linked to this syndrome (COL2A1, COL9A1, COL9A2, COL9A3, COL11A1, and COL11A2), followed by Ullrich congenital muscular dystrophy, with four collagens associated (COL6A1, COL6A2, COL6A3, and COL12A1)." (PMID 37189830, 2023). "Mutations in COL6A1, COL6A2, and COL6A3 lead to the severe Ullrich Congenital Muscular Dystrophy (UCMD) and a spectrum of disease of varying severity including the milder Bethlem muscular dystrophy." (PMID 40225172, 2023). "Ullrich congenital muscular dystrophy (UCMD) is a rare disease caused by mutations in the COL6A1, COL6A2 or COL6A3 genes leading to deficiency of collagen VI in extracellular matrices (ECM)." (PMID 35925158, 2022). "Deficiency of collagen type VI (Col VI) caused by mutations of COL6 genes (COL6A1, COL6A2, and COL6A3) gives rise to three main muscle disorders: Bethlem myopathy (BM), Ullrich congenital muscular dystrophy (UCMD), and myosclerosis myopathy." (PMID 33086603, 2020). "Ullrich congenital muscular dystrophy (UCMD), Bethlem myopathy (BM), and myosclerosis myopathy (MM) are diseases caused by mutations in each of the three genes (COL6A1, COL6A2, and COL6A3) encoding the extracellular matrix protein collagen VI." (PMID 32053901, 2020). "Mutations in COL6A1, COL6A2 and COL6A3 encoding collagen VI, cause Ullrich congenital muscular dystrophy (UCMD), Bethlem myopathy (BM) and myosclerosis myopathy." (PMID 25158062, 2014). "Deficiency of ColVI due to mutations in COL6A1, COL6A2, or COL6A3 gives rise to three main muscle disorders, Ullrich congenital muscular dystrophy (UCMD, MIM #254090), Bethlem myopathy (BM, MIM #158810), and myosclerosis myopathy (MIM #255600)." (PMID 25477819, 2014). "Mutations in the genes encoding collagen VI (COL6A1, COL6A2 and COL6A3) result in two major phenotypes: Bethlem myopathy [BM, OMIM #158810] and Ullrich congenital muscular dystrophy [UCMD, OMIM #254090]." (PMID 20302629, 2010). "Mutations in any of the three collagen 6A genes COL6A1, COL6A2 and COL6A3 result in Ullrich congenital muscular dystrophy (UCMD), Bethlem myopathy (BM) or phenotypes intermediate between UCMD and BM, characterised by a combination of distal laxity, proximal muscle weakness and joint contractures." (PMID 22075033, 2012). "Mutations in the COL6A1, COL6A2, and COL6A3 genes cause collagen VI-related myopathies (COL6-RM) that include Ullrich congenital muscular dystrophy (UCMD), Bethlem myopathy (BM), and myosclerosis myopathy (MM)." (PMID 37047652, 2023).
Ullrich congenital muscular dystrophy (continued). "Mutations in COL6A1, COL6A2, and COL6A3 lead to a spectrum of collagen VI-related muscular dystrophies, ranging from the severe Ullrich congenital muscular dystrophy (UCMD) via intermediate phenotypes to the milder Bethlem muscular dystrophy (BM)." (PMID 40225172, 2023). "Mutations in the COL6A1, COL6A2, and COL6A3 genes result in either the absence or malformation of the microfibrils, causing a spectrum of muscle disorders: Bethlem myopathy (BM, MIM 158810), Ullrich congenital muscular dystrophy (UCMD, MIM 254090), and myosclerosis myopathy (MM, MIM 255600)." (PMID 37569848, 2023). "Mutations in genes encoding collagen VI (i.e., COL6A1, COL6A2, and COL6A3) have been identified as causative in Ullrich congenital muscular dystrophy (UCMD) and Bethlem myopathy (BM)." (PMID 26753503, 2016). "Ullrich congenital muscular dystrophy (UCMD) is caused by mutations in collagen VI genes (COL6A1, COL6A2 and COL6A3) and is characterised by congenital hypotonia, proximal muscle weakness and distal joint hyperlaxity." (PMID 26670220, 2015). "Mutations in COL6A1, COL6A2 and COL6A3 genes result in collagen VI myopathies: Ullrich congenital muscular dystrophy (UCMD), Bethlem myopathy (BM) and intermediate phenotypes." (PMID 22075033, 2012). "Dominant-negative mutations in the genes that encode the three major α chains of collagen type VI, COL6A1, COL6A2, and COL6A3, account for more than 50% of Ullrich congenital muscular dystrophy patients and nearly all Bethlem myopathy patients." (PMID 28918041, 2017). "Mutations of COL6 genes (COL6A1, COL6A2, and COL6A3) cause COL6-related myopathies, a group of rare inherited muscle diseases that include Bethlem myopathy (BM) and Ullrich congenital muscular dystrophy (UCMD), as well as the limb girdle and myosclerosis myopathy variants." (PMID 27656840, 2016). "In humans, mutations in any of the three genes coding for collagen VI (COL6A1, COL6A2, COL6A3) result in defective ECM composition and cause a wide clinical spectrum of collagen VI myopathies including Ullrich congenital muscular dystrophy (UCMD), Bethlem myopathy (BM) and myosclerosis myopathy." (PMID 23437220, 2013).
Bethlem myopathy (22 papers, 2010 to 2025). A usually autosomal dominant inherited movement disorder caused by mutations in the COL6A1, COL6A2, and COL6A3 genes. "Finally, an intriguing clinical case of a single patient with COL6A2-associated Bethlem myopathy also suggests that mutations in introns can lead to allele bias and disease." (PMID 34764277, 2021). "The final diagnosis of UCMD type 1 was made by genetic analysis, and COL6A2 showed a variety of phenotypes ranging from milder Bethlem myopathy to more severe UCMD." (PMID 38065855, 2023). "For example, COL6A2 and COL6A3 jointly encode type VI collagen, and their mutation will lead to an autosomal dominant disease, namely Bethlem myopathy." (PMID 35872873, 2022). "Four families had mutations in COL6A2 and COL6A3, typically associated with Bethlem myopathy, but recently also found in LGMD-like cases." (PMID 29970176, 2018). "Bethlem myopathy is almost exclusively caused by dominant COL6A1, COL6A2, or COL6A3 mutations, whereas UCMD occurs as a result of both recessive and dominant mutations." (PMID 28918041, 2017). "SNV analysis also revealed a missense Variant of Uncertain Significance (VUS) in 1 UMD and 1 suspected LGMD case in COL6A2 (P52) and COL6A1 (P97) gene, respectively which causes Bethlem myopathy 1 (LGMD R22 Collagen6-related) disease as per the Clinvar database." (PMID 34925456, 2021). "Even though phenotypic overlap between patients with COL12A1‐related myopathy and patients with Bethlem myopathy, a form of COL6‐related dystrophy due to mutations in collagen VI genes (COL6A1, COL6A2, or COL6A3) has been noted, several features help distinguish these disorders." (PMID 31509352, 2019). "Some heterozygous premature termination codon (PTC) mutations in COL6A1 cause Bethlem myopathy but they are non-pathogenic when they occur in COL6A2/COL6A3." (PMID 31387942, 2019).
breast carcinoma (12 papers, 2011 to 2025). "COL6A2, which encodes the α2 chain of COL6, has been found to be highly expressed in multiple cancers, including glioma, breast cancer, lung cancer, colorectal cancer, and gastric cancer 19-27." (PMID 41323784, 2025). "Second, the TCGA BRCA dataset (n = 821) with PAM50 subtypes called by RNAseq was used to validate the differentially expression of COL2A1, COL11A1, COL6A1, COL6A2, THBS1 and LUM among four breast cancer molecular subytpes in an independent cohort." (PMID 40927672, 2025). "Disease-specific survival discrepancy was observed comparing breast cancer patients of the upper and lower quartile of the collagen family (COL2A1, COL11A1, COL6A1, COL6A2), THBS1 and LUM gene expression signature (log-rank test, P = 0.06)." (PMID 40927672, 2025). "Established markers for breast cancer cells (BRCA1, MAP3K1, BMPR1A) and fibroblasts (FN1, VIM, COL6A2) were used to classify the clusters." (PMID 39805002, 2025). "Among the identified transcripts, downregulation of COL6A2, SERPINA1, CCBE1, TFPI2, THBS1 and COL8A1 have been shown to promote migration and invasion of malign breast cancer cells, aggravate metastatic spread and result in poor prognosis of breast cancer patients." (PMID 31848385, 2019). "In these terms, aside from the genes COL4A6, COL6A2 and COL14A1 belonging to the collagen family, Tenascin-X (TNXB), which was described as a metastasis signature in breast cancer, was also up-regulated in our experiment but has not previously been reported for gastric cancer." (PMID 21435268, 2011).
muscular dystrophies (8 papers, 2019 to 2025). "Other ECM-related genes, POSTN (Periostin) and COL6A2 (Collagen, type VI, alpha), are also appealing candidates as they have been directly linked to myogenesis and muscular dystrophy, respectively." (PMID 38413582, 2024). "In addition, Mstn, the gene encoding myostatin, was downregulated in Col6a2–/– muscle, a finding consistent with other models of muscular dystrophy." (PMID 40309777, 2025). "Among other muscular dystrophies, 20 of 24 patients (83.3%) had variants in LAMA2 (n = 6), LMNA (n = 5), COL6A1 (n = 4), CHKB (n = 2), COL6A2 (n = 2), and COL6A3 (n = 1)." (PMID 40494860, 2025). "Col6a2–/– mice have a normal lifespan but develop muscle atrophy and weakness with histological hallmarks of muscular dystrophy and fibrosis." (PMID 40309777, 2025). "Collagen VI–related disorders (COL6-RDs) are a group of rare muscular dystrophies caused by pathogenic variants in collagen VI genes (COL6A1, COL6A2, and COL6A3)." (PMID 40309777, 2025). "The remaining six families had pathogenic variants in genes usually associated with muscular dystrophies (HNRNPDL, TOR1AIP1, SGCG, COL6A2, CAV3, TRIP4)." (PMID 38982518, 2024). "Multiple genes with high loading in LF1 relate to muscular dystrophy with the Dmd gene ranking in top 100 genes, and all 3 Col6a genes (Col6a1, Col6a2 and Col6a3 genes) responsible for Ulrich muscular dystrophy are present in the top 40 genes in LF1." (PMID 37000843, 2023). "Congenital myopathies and muscular dystrophies yielded a comparable ‘solved’ rate of 53%, spanning 16 genes, including known variants in STAC3, RYR1 and COL6A2/3 in addition to 21 novel variants across 14 genes." (PMID 37516995, 2023). "Because gene mutations in COL6A1, COL6A2 and COL6A3 have been shown to result in muscular dystrophy, which indicated that collagen VI is particularly necessary for the vitality of skeletal muscle." (PMID 31286980, 2019).
glioma (7 papers, 2021 to 2025). A benign or malignant brain and spinal cord tumor that arises from glial cells (astrocytes, oligodendrocytes, ependymal cells). "Multiple-database and tissue microarray analyses showed that COL6A2 expression in glioma was associated with poor prognosis, Tissue microarray showed that COL6A2 was the highest expressed in WHO IV and significantly higher in TCGA-GBM than in TCGA-LGG." (PMID 36505882, 2022). "Among them, 28 COL6A2 genes were significantly related to survival rate in TCGA glioma patients (P < 0.01), including 1 low-risk immunostimulatory gene (hazard ratio (HR) < 1) and 27 high-risk immunostimulatory genes (HR > 1)." (PMID 36505882, 2022). "Obviously, COL6A2 is associated with these immunomodulatory genes and promotes the malignant progression of glioma." (PMID 36505882, 2022). "In addition, the associations of COL6A2 with the clinical characteristics of glioma patients were examined, and COL6A2 was highly expressed in wild type IDH cases (p<0.001)." (PMID 36505882, 2022). "The associations of COL6A2 expression with immunomodulatory genes in glioma were examined." (PMID 36505882, 2022). "COL6A2 may be a novel potential prognostic biomarker of glioma and associated with tumor-infiltrating immune cells in the tumor microenvironment, and interference with COL6A2 expression can inhibit tumor growth, which suggests COL6A2 as a potential target for future treatment." (PMID 36505882, 2022). "Patients were divided into two groups, including low- (IRS ≤ 7) and high- (IRS ≥ 8) COL6A2 expression groups, and COL6A2 in glioma tissue microarray (TMA) was detected by IHC." (PMID 36505882, 2022). "The expression of COL6A2 was significantly higher in glioblastoma compared with other types of glioma." (PMID 36505882, 2022). "Considering the important function of COL6A2, its expression levels were examined in various stages of glioma." (PMID 36505882, 2022). "In this study, we found that COL6A2 has prognostic significance in glioma patients through a multi-database combination, Western blot, qPCR and immunohistochemistry suggested high COL6A2 expression in glioma." (PMID 36505882, 2022). "The relationship between immune infiltration and somatic CNV regarding the expression of COL6A2 in glioma, the results show that the copy number of COL6A2 has different degrees of infiltration relationship with T cell CD8+, T cell CD4+, DC, etc." (PMID 36505882, 2022). "Western blot, real-time PCR, a tissue microarray and immunohistochemistry were applied to detect COL6A2 mRNA and protein amounts in glioma, and all experiments were repeated three times." (PMID 36505882, 2022). "In receiver operating characteristic (ROC) analysis of COL6A2, AUC values for 1-, 3-, and 5-year survival were 0.739, 0.794, and 0.796 in glioma, respectively." (PMID 36505882, 2022). "Based on the mRNA expression of COL6A2, patients with glioma in TCGA were divided into the low and high COL6A2 expression groups, and GO and KEGG pathway analyses were performed." (PMID 36505882, 2022). "Kaplan Meier analysis based on TCGA database, GEO database, CGGA database and tissue microarray showed that COL6A2 was a prognostic factor in glioma patients." (PMID 36505882, 2022). "In patients with recurrent gliomas, COL6A2 was also highly expressed." (PMID 36505882, 2022). "Taken together, these results suggested that the expression of COL6A2 could predict glioma prognosis." (PMID 36505882, 2022). "However, further experiments and clinical trials are essential to clarify the therapeutic value of COL6A2 in glioma." (PMID 36505882, 2022). "Our research firstly identified COL6A2 as a potential prognostic biomarker in glioma." (PMID 36505882, 2022). "Moreover, COL6A2 was detected in glioma tissues by immunohistochemistry and Significant differences in WHO IV expression." (PMID 36505882, 2022). "Real-time PCR was performed to assess the mRNA expression of COL6A2 in glioma cells." (PMID 36505882, 2022).